ALDH7A1 (aldehyde dehydrogenase 7 family member A1)
Diseases named in the same sentence as ALDH7A1 in open-access papers (continued):
Sharing a sentence is not in itself a finding about the gene and the disease.
pancreatic ductal adenocarcinoma (4 papers, 2021 to 2025). An infiltrating adenocarcinoma that arises from the epithelial cells of the pancreas. "H&E-stained pancreas histology images suggested that Aldh7a1 knockout remarkably suppressed the progression of pancreatic ductal adenocarcinoma." (PMID 33537098, 2021). "And acinar-duct metaplasia (ADM), PanIN and pancreatic duct adenocarcinoma lesions of Aldh7a1-/-; KPC mice was reduced approximately 40% compared to the KPC mice." (PMID 33537098, 2021). "Rationale: The activity of aldehyde dehydrogenase 7A1 (ALDH7A1), an enzyme that catalyzes the lipid peroxidation of fatty aldehydes was found to be upregulated in pancreatic ductal adenocarcinoma (PDAC)." (PMID 33537098, 2021). "ALDH7A1 knockdown significantly reduces tumor formation in pancreatic ductal adenocarcinoma." (PMID 36531021, 2022).
colon carcinoma (3 papers, 2015 to 2021). "This speculation is supported by several pieces of evidence, demonstrating a specific elevated expression of ALDH1B1 in colon cancer; ALDH3B1 in lung, breast, ovarian, and colon cancer; ALDH3A1 in lung cancer; and ALDH7A1 in prostate cancer." (PMID 35582039, 2020).
developmental and epileptic encephalopathies (3 papers, 2022 to 2025). "In 2022, the International League Against Epilepsy (ILAE) classified PDE as a cause-specific epilepsy syndrome and named it pyridoxine dependent (ALDH7A1) – developmental and epileptic encephalopathies, PD-DDE." (PMID 40979201, 2025).
non-small cell lung carcinoma (3 papers, 2017 to 2022). A group of at least three distinct histological types of lung cancer, including non-small cell squamous cell carcinoma, adenocarcinoma, and large cell carcinoma. "Positive ALDH7A1 protein staining correlates with increased cancer recurrence in non-small cell lung carcinoma." (PMID 30486822, 2018).
osteoporosis (3 papers, 2010 to 2023). A condition of reduced bone mass, with decreased cortical thickness and a decrease in the number and size of the trabeculae of cancellous bone (but normal chemical composition), resulting in increased fracture incidence. "In summary, using data from over 11,500 individuals, we have identified and validated ALDH7A1 as a novel susceptibility candidate gene for osteoporosis." (PMID 20072603, 2010). "However, regardless of this differential effect, the significant association results we identified both for BMD and OF risk strongly support the potential contribution of ALDH7A1 to the pathogenesis of osteoporosis." (PMID 20072603, 2010). "Further studies are warranted to explore the generality of our findings for ALDH7A1 identified by GWAS to other populations, and to determine the mechanisms by which this gene and its products contribute to the pathogenesis of osteoporosis." (PMID 20072603, 2010). "Only a few osteoporosis GWAS have been reported in Asian, which have identified a few specific genes like JAG1 and ALDH7A1." (PMID 21573128, 2011).
ovarian tumors (3 papers, 2012 to 2025). "The available literature supports that ALDH1A3, ALDH3A2, and ALDH7A1 isozymes are expressed more abundantly in ovarian tumors, particularly in mucinous and endometrioid type tumors." (PMID 30965686, 2019). "Immunohistochemical staining showed significant overexpression of ALDH1A3, ALDH3A2, and ALDH7A1 isozymes in ovarian tumors relative to normal ovarian tissues." (PMID 22852552, 2012).
pancreatic cancer (3 papers, 2016 to 2022). "Taken together, these results suggest that ALDH7A1 deficiency causes a significant reduction in pancreatic cancer progression of mice, implying the critical role of ALDH7A1 in PDAC." (PMID 33537098, 2021). "Although the mRNA level of ALDH7A1 is associated with poor survival of pancreatic cancer patients, further investigation may reveal protein level of ALDH7A1 and expression cell types." (PMID 33537098, 2021). "EPS8 increased polyubiquitination by downregulating ALDH7A1 protein expression in pancreatic cancer." (PMID 36237305, 2022). "Colony formation of pancreatic cancer cell lines were reduced average 64% and 85% by ALDH7A1 knockdown in MIA PaCa-2 and AsPC-1 respectively." (PMID 33537098, 2021).
status epilepticus (3 papers, 2015 to 2023). Status epilepticus is defined as a continuous seizure lasting more than 30 min, or two or more seizures without full recovery of consciousness between any of them. "A significant proportion of patients reported febrile seizures or recurrent episodes of status epilepticus during acute febrile infections, especially in those with ALDH7A1 deficiency." (PMID 36980111, 2023). "In S28, we identified a 1-bp homozygous deletion in aldehyde dehydrogenase 7 family, member A1 (ALDH7A1), which may better explain the reported neonatal seizures and medically resistant status epilepticus in this patient." (PMID 25356967, 2015).
cervical cancer (2 papers, 2021 to 2022). A primary or metastatic malignant neoplasm involving the cervix. "Besides that, low transcript levels retrieved from TCGA primary tumors for three of the 11 ‘hub proteins’ (ALDH7A1, GOT1, MTHFD1) were associated with poor overall survival in renal and cervical cancer (p-value ≤ 0.05; Human Protein Atlas platform)." (PMID 34186243, 2021). "ALDH7A1 was among 30 genes that demonstrated a dose–response pattern with NNK, a tobacco carcinogen, in cervical cancer samples, implicating tobacco may be a causative factor in cervical cancer development in addition to HPV infection." (PMID 35574500, 2022).
cognitive delay (2 papers, 2023 to 2024). "In other cases, the selective impairment of isolated functions (motor developmental delay and normal IQ in 4 patients with ALDH7A1 deficiency, isolated language delay in 11 patients) was demonstrated." (PMID 36980111, 2023).
glioma (2 papers, 2017 to 2021). A benign or malignant brain and spinal cord tumor that arises from glial cells (astrocytes, oligodendrocytes, ependymal cells). "Analysis of the TCGA dataset showed that ALDH16A1, ALDH3B1, ALDH1A3, ALDH3A1, ALDH7A1 were significantly increased in IDH wildtype gliomas, while ALDH2, ALDH6A1, ALDH5A1, ALDH1A1, ALDH1L2, ALDH18A1, ALDH1B1 expression were higher in IDH mutant gliomas than IDH wildtype gliomas." (PMID 35116021, 2021).
glutaric aciduria type 1 (2 papers, 2022 to 2025). "MALDI-MSI and MALDI-IRIS were used to study two related IMDs inthe l-lysine catabolism pathway: pyridoxine-dependent epilepsy(PDE-ALDH7A1) and glutaric aciduria type 1 (GA1).These disorders are caused by mutations in ALDH7A1 and GCDH, which encode the enzymes antiquitin and GCDH, respectively." (PMID 40521743, 2025).
hepatocellular carcinoma (2 papers, 2018 to 2025). A malignant tumor that arises from hepatocytes. "We used ALDH7A1 antibody IHC on tissue arrays that pair the tumor samples with adjacent normal tissue for hepatocellular carcinoma (HCC) and renal clear cell carcinoma (ccRCC)." (PMID 30486822, 2018). "Analysis of cancer RNAseq data from TCGA showed that low ALDH7A1 mRNA levels correlate with a low PPAR activity signature, and with poor survival prognosis in patients with hepatocellular carcinoma and renal clear cell carcinoma." (PMID 30486822, 2018).
Hypsarrhythmia (2 papers, 2022). Hypsarrhythmia is abnormal interictal high amplitude waves and a background of irregular spikes. "Vitamin B6 allowed patients with ALDH7A1 and PNPO mutations to achieve seizure-free status, oxcarbazepine was effective for patients with SCN2A, ATP7A, WWOX, and PRRT2 mutations, and ACTH was partly effective for DOCK6 mutation patients with spasms and hypsarrhythmia." (PMID 35715422, 2022).
liver cancer (2 papers, 2018 to 2020). An epithelial or non-epithelial malignant neoplasm that arises from the liver. "Analysis of publically available cancer gene expression data revealed that ALDH7A1 mRNA levels were reduced in many human cancers, and that this correlated with poor survival in kidney and liver cancer patients." (PMID 30486822, 2018). "The three-way correlation between ALDH7A1 expression, PPAR activity and clinical outcome appears to be a feature of kidney and liver cancers, but not other cancer types." (PMID 30486822, 2018).
oral cancer (2 papers, 2019 to 2022). "We found that oral cancer patient who carry allele mutation (AG) of rs13182402 polymorphism have significantly higher mRNA levels of ALDH7A1 compare to AA genotype." (PMID 35613852, 2022). "The incidences of ALDH7A1 rs13182402 and rs12659017 polymorphism between the patients with oral cancer and healthy controls were comparable." (PMID 35613852, 2022). "Furthermore, to realize correlation between the mRNA level of ALDH7A1 and rs13182402 polymorphism, quantitative real time-PCR (qPCR) were used to analyze ALDH7A1 mRNA level in cancer tissue of 30 oral cancer patients." (PMID 35613852, 2022). "Moreover, oral cancer patient who carry allele mutation (AG) of rs13182402 polymorphism have significantly higher mRNA levels of ALDH7A1 compare to AA genotype." (PMID 35613852, 2022). "In our study, ALDH7A1 rs13182402 allele mutation, which was detected from the whole-blood genomic DNA, was an independent favorable prognostic factor for nodal metastasis in oral cancer." (PMID 35613852, 2022). "It hinted ALDH7A1 rs13182402 mutation, associated with high ALDH7A1 expression, might be a favorable prognostic factor for patients with oral cancer." (PMID 35613852, 2022). "Based on this study, we discovered the impact and functions of ALDH7A1 polymorphism in oral cancer." (PMID 35613852, 2022). "For this purpose, the influences of ALDH7A1 rs13182402 and rs12659017 on oral cancer development and prognosis were analyzed." (PMID 35613852, 2022). "Although patients with oral cancer who had lower ALDH7A1 expression had poorer prognoses than those with higher expression did, individual allele functions should be validated in vitro." (PMID 35613852, 2022). "Oral cancer tissues and five oral cancer cell lines (SCC-14, SAS, CA9-22, HSC-3, and OECM-1) were used to investigate the correlations of ALDH7A1 rs13182402 polymorphisms and ALDH7A1 expression levels." (PMID 35613852, 2022). "ALDH7A1 rs13182402 also corresponded to higher expressions in upper aerodigestive mucosa, whole blood, the musculoskeletal system and oral cancer tissues than did the ALDH7A1 wild type." (PMID 35613852, 2022). "The prognostic influence of ALDH7A1 SNPs in oral cancer was also analyzed." (PMID 35613852, 2022). "The gene encoding aldehyde dehydrogenase 7 family member A1 (ALDH7A1) has been associated with the development and prognosis in multiple cancers; however, the role of ALDH7A1 polymorphisms in oral cancer remains unknown." (PMID 35613852, 2022). "However, ALDH7A1 rs13182402 represented an independent favorable prognostic factor for nodal lymph node metastasis in patients with oral cancer who chewed betel quid." (PMID 35613852, 2022). "In conclusion, this study reported that ALDH7A1 SNPs, detected from the whole-blood genomic DNA, did not affect the risk of oral cancer." (PMID 35613852, 2022). "In our study, both ALDH7A1 rs13182402 and rs12659017 were not discovered to constitute risk factors for oral cancer development." (PMID 35613852, 2022). "Furthermore, ALDH7A1 overexpression in oral cancer cells increased in vitro migration, whereas its silencing reduced cell migration." (PMID 35613852, 2022). "ALDH7A1 polymorphisms did not influence the risk of oral cancer for all participants, alcoholic drinkers, or betel quid chewers." (PMID 35613852, 2022). "Among these oral cancer cell lines, we observed that SAS cells expressed higher ALDH7A1 levels than SCC-14, CA9-22, HSC-3 and OECM-1 cells." (PMID 35613852, 2022).
acute leukemia (1 paper, 2020). A clonal (malignant) hematopoietic disorder with an acute onset, affecting the bone marrow and the peripheral blood. "ALDH7A1 is also a known cancer stem cell marker for multiple myeloma, acute leukemia, and brain tumors." (PMID 32256979, 2020).
coloboma (1 paper, 2014). An abnormality in which a part of a structure in one or both eyes is missing. "We show that morpholino knockdown of aldh7a1 in zebrafish causes uveal coloboma and misregulation of nlz1, another known contributor to the coloboma phenotype, as well as skeletal abnormalities." (PMID 25004007, 2014). "Knockdown of aldh7a1 by Aldh7a1 MO1in zebrafish embryos resulted in bent tail; coloboma of the eye evident at 28 hpf which persists until at least 5–6 days post-fertilization (dpf) compared to control embryos where the optic fissure had nearly fused at 28 hpf." (PMID 25004007, 2014). "These existing connections of RA to coloboma led us to pursue it as a chemical that is potentially involved in the aldh7a1 pathway." (PMID 25004007, 2014). "However, co-injection of Aldh7a1 MO1 and Aldh7a1 MO2 also resulted in coloboma, but with lower total concentrations of MO compared to controls." (PMID 25004007, 2014).
endometrial cancer (1 paper, 2024). Primary or metastatic malignant neoplasm involving the endometrium (mucous membrane that lines the endometrial cavity). "The proteomic profiling of endometrial cancer cell lines revealed that ECC-1 and RL95-2 shared the ALDH isoforms ALDH3A1, ALDH3A2, ALDH3B1, ALDH3B2, ALDH7A1, ALDH9A1, and ALDH18A1 in their proteome." (PMID 38893151, 2024).
hyperplasia (1 paper, 2016). An abnormal increase in the number of cells in an organ or a tissue with consequent enlargement. "ALDH7A1 also exhibited differential localization; while cytoplasmic staining was observed for both PrCa and BPH sections, the nuclear staining was greater in the PrCa sections and decreased in the BPH section (3e, carcinoma; 3f, hyperplasia)." (PMID 27764770, 2016).
Intellectual disability (1 paper, 2025). "Classical PDE caused by ALDH7A1 variants frequently results in intellectual disability due to accumulation of neurotoxic intermediates (α-aminoadipic semialdehyde and piperideine-6-carboxylate) even when seizures are controlled." (PMID 41300786, 2025).
ischemic stroke (1 paper, 2022). A stroke disorder caused by obstruction of blood flow to the brain, due to thrombotic (local blood clot formation) or embolic (due to a blood clot or other material traveling from another site) event. "The underlying mechanism is that ALDH7A1 mutations can cause oxidative stress, inflammation, and vitamin B6 deficiency and therefore result in ischemic stroke." (PMID 36258220, 2022). "The main finding of our study suggests that the ALDH7A1 rs12514417 TG + GG genotype is associated with a 1.6-fold increased risk of ischemic stroke in subjects who drink more than 150 ml of alcohol per week." (PMID 36258220, 2022). "Here, we evaluated the association of ischemic stroke with rs12514417 polymorphism of the alcohol metabolizing gene, aldehyde dehydrogenase 7A1 (ALDH7A1) and alcohol consumption." (PMID 36258220, 2022). "This is the first study to identify the relationship between ALDH7A1 mutation and ischemic stroke, suggesting a change in lifestyle, specifically a reduction in alcohol consumption could reduce disease risk in carriers of this variant." (PMID 36258220, 2022).
kidney cancer (1 paper, 2018). Primary or metastatic malignant neoplasm involving the kidney. "(C) Cox proportional hazard regression analysis of the association between ALDH7A1 mRNA and EGFR levels for liver and kidney cancer." (PMID 30486822, 2018). "Overall, these findings suggest that low ALDH7A1 expression might be a useful independent predictor of clinical outcome in liver and kidney cancers." (PMID 30486822, 2018). "Why are liver and kidney cancer sensitive to the effects of low ALDH7A1?" (PMID 30486822, 2018).
liver fibrosis (1 paper, 2017). "Furthermore, it also suggested that the alteration of ALDH1B1, ALDH2 and ALDH7A1 levels may be potential biomarkers for the curative effect evaluation of gypenoside against liver fibrosis." (PMID 28291813, 2017).
lung squamous cell carcinoma (1 paper, 2025). "Recent findings have shown ALDH7A1 expression in PDAC can additionally be regulated post-transcription through interaction with epidermal growth factor receptor kinase substrate 8 (EPS8), inhibiting proteasomal degradation, and via DNA-methylation in lung squamous cell carcinoma." (PMID 40524738, 2025).
molybdenum cofactor deficiency (1 paper, 2025). "ALDH7A1 can also be inhibited by accumulating sulphite in sulphite oxidase (SUOX) or molybdenum cofactor deficiency (MoCD) thereby eliciting a secondary ALDH7A1 deficiency." (PMID 39038845, 2025).
osteosarcoma (1 paper, 2025). A usually aggressive malignant bone-forming mesenchymal neoplasm, predominantly affecting adolescents and young adults. "Our study highlights a strong correlation between glycerolipid metabolism and osteosarcoma prognosis, identifying AGPAT3 and ALDH7A1 as key genes associated with patient outcomes." (PMID 41502512, 2025). "We found that low expression of AGPAT3 and ALDH7A1 is significantly correlated with poor prognosis in osteosarcoma patients." (PMID 41502512, 2025). "Glycerolipid metabolism-related genes 1-acylglycerol-3-phosphate O-acyltransferase 3 (AGPAT3) and aldehyde dehydrogenase 7 family member A1 (ALDH7A1) were identified as key prognostic genes in osteosarcoma, with high AGPAT3 expression correlating with improved survival." (PMID 41502512, 2025). "Genes AGPAT3 and ALDH7A1 in the glycerolipid metabolic pathway may serve as prognostic markers and play key roles in osteosarcoma." (PMID 41502512, 2025). "However, further research is required to illustrate the function of ALDH7A1 in osteosarcoma." (PMID 41502512, 2025). "In osteosarcoma, the combination of AGPAT3 or ALDH7A1 may be used to predict the prognosis." (PMID 41502512, 2025).
ovarian carcinoma (1 paper, 2018). A malignant neoplasm originating from the surface ovarian epithelium. "High ALDH7A1 protein expression has been reported in ovarian cancer, with highest expression in invasive ovarian cancer cells comparing to healthy ovarian epithelia." (PMID 30486822, 2018).
papilloma (1 paper, 2023). A benign epithelial neoplasm that projects above the surrounding epithelial surface and consists of villous or arborescent outgrowths of fibrovascular stroma. "We also investigated the protein expression level of these mutations, the results showed four proteins (HRAS, ALDH7A1, CBLB, and MPRIP) were differently expressed between papilloma and PUC." (PMID 37704624, 2023).
PNPO deficiency (1 paper, 2025). "Beyond classic ALDH7A1 mutations causing (PDE) and pyridox(am)ine-5’-phosphate oxidase (PNPO deficiency), the recent characterization of additional metabolic disorders—including hypophosphatasia and homocystinuria—has broadened the spectrum of vitamin B6-dependent epileptic syndromes." (PMID 41149778, 2025).
prostate adenocarcinoma (1 paper, 2016). "Significantly, these cultured human prostate adenocarcinomas also contained cells with stem-like properties as shown by expression of CD133, CD44, ALDH7A1, CK5/14 and α2β1 antigens." (PMID 27764770, 2016).
renal clear cell carcinoma (1 paper, 2018). "Low ALDH7A1 protein levels correlated with poor clinical outcome in hepatocellular and renal clear cell carcinoma patients." (PMID 30486822, 2018). "Immunohistochemical staining of clinical samples suggests that low ALDH7A1 expression may be a useful prognostic marker of poor clinical outcome for hepatocellular and renal clear cell carcinomas." (PMID 30486822, 2018). "We provide evidence that low ALDH7A1 expression is a useful prognostic marker of poor clinical outcome for hepatocellular and renal clear cell carcinomas and hypothesize that patients with low ALDH7A1 might benefit from therapeutic approaches addressing PPARα activity." (PMID 30486822, 2018).